ITGB1-DT (ITGB1 divergent transcript)
Synonyms: LincIN
Gene: Long non-coding RNA gene on chromosome 10 (32,958,390 to 33,134,921, forward strand). Ensembl gene ENSG00000229656.
Diseases named in the same sentence as ITGB1-DT in open-access papers:
ITGB1-DT is named in the same sentence as 4 diseases in open-access papers, as found by Europe PMC text mining. Sharing a sentence is not in itself a finding about the gene and the disease.
ITGB1-DT shares sentences with these, for which no sentence is quoted: breast carcinoma (3 papers); tumor (2); breast tumor (1); cancer (1).